CD4 (CD4 molecule)
Diseases named in the same sentence as CD4 in open-access papers (continued):
Sharing a sentence is not in itself a finding about the gene and the disease.
infection (continued). "CD4+ and CD8+ T-cell mediated responses are important for viral clearance in both infections." (PMID 36298538, 2022). "In our case report, this RA-HIV patient was treated with adalimumab throughout, and HIV-RNA and CD4+ counts remained stable during the one year follow-up without the new infection." (PMID 35990692, 2022). "We found that NK cell-depletion prior to T1L infection did not alter Treg responses but did diminish Th1 CD4+ T cell responses." (PMID 35993365, 2022). "To examine pathogen-specific CD4+ and CD8+ effector T cells during infection, we restimulated splenocytes and liver cells from infected mice with an MHC class II–restricted listeriolysin O peptide (LLO190–201) and an MHC class I–restricted OVA peptide OVA257–264 (SIINFEKL), respectively." (PMID 36106640, 2022). "The involvement of Chlamydia-specific Th1 cells is further questioned by the absence of T-bet expression in CD4 T cells within the FRT during the period of infection control." (PMID 35196366, 2022). "This may explain mild symptoms, or asymptomatic infection, in HIV individuals with higher CD4+ levels." (PMID 36355894, 2022). "The percent of IFN-γ positive CD4+ and CD8+ T cells was also greater in ΔG infection." (PMID 35958551, 2022). "When C57BL/6 mice were infected with the ME49 strain of T. gondii, activated (CD44hiCD62Llo) CD4+ and CD8+ T cell number in the ILNs was greatest during acute infection (2 wpi), consistent with the broad distribution of parasite in peripheral tissues at this time point." (PMID 36541708, 2022). "Although the mechanisms of CD4+ preference over CD8+ are still unknown, it is clear that the CD4+-lymphocyte immune response is necessary for protection against natural infection or under conditions of artificial immunization." (PMID 36277070, 2022). "We stimulated CD4+ T cells from three different donors with equimolar concentrations of IL-2 and IL-15 and analyzed the expression of CDK9 and cyclin T1 after 8 to 9 days of stimulation, a time when latent and productive infection with HIV-GKO was measured." (PMID 35499323, 2022). "We observed increased expression of intracellular IFN-γ in NK cells, CD4+ T cells, and CD8+ T cells from Alk1fl/flVav1Cre mice 24 hours after infection, which coincided with higher bacterial counts in the livers and spleens of Alk1fl/flVav1Cre mice than in Alk1fl/fl mice." (PMID 34874921, 2022). "During the transition from naive CD4+ T cells to TfhD3 under HIVYu2b infection, we observed no downregulation of PRDK2 and BACH2, two inhibitors of the Tfh cell program." (PMID 34984326, 2022). "Cross-protection due to neutralizing antibodies resulting from CD4 T cell expansion following infection after JEV immunization, but not with YF immunization, has also been reported against ZIKV and DENV." (PMID 36298768, 2022). "However, CnpB induced significant Th1/Th2 cellular immune responses with a decreased number of T and B cells in the lungs, and significantly recruits of CD4+ and CD8+ T cells after M. tuberculosis attenuated strain H37Ra infection." (PMID 35811674, 2022). "All together, these results suggest that among blood and tonsillar memory CD4+ T cells, those with the highest levels of fucose and sialic acid are preferentially targeted for infection by HIV; this phenomenon was however not observed among endometrial cells." (PMID 35787792, 2022). "Still, a strong T lymphocyte response will not be enough to eliminate infection, but all neutralizing antibodies and the CD4+ and CD8+ T lymphocyte respond together." (PMID 36014985, 2022). "Moreover, we provide the evidence that neutrophils are capable of modulating CD4+ and CD8+ T-cell proliferation and IFN-γ production in different ways depending on the time of infection." (PMID 35185880, 2022).
infection (continued). "HIV infection induces apoptosis in CD4+ andCD4DIMCD8BRIGHT T cells: To determine the extent of HIV-induced cell death, we infected activated PBMCs with HIV and measured apoptosis 6 days post infection using an annexin/PI flow-based assay." (PMID 35891449, 2022). "Additionally, the existing vaccine booster jab protects against symptomatic or asymptomatic infection, transmission, and severe infection by promoting specific CD8+ or CD4+ T‐cell response." (PMID 35349754, 2022). "More detailed analysis of CD4+ T cell subsets revealed reduced frequencies of T-helper type 1 (Th1), Th17, regulatory T cells (Treg) and follicular helper T cells (TFH) at 72 h in P+ participants, suggesting T cell migration towards the site of infection." (PMID 35140232, 2022). "Here, we provide in vivo evidence of functional significance whereby deletion of LEC MHC-II led to decreased seeding and aberrant phenotypes of CD4+ TRM cells around conducting airways, with diminished recruitment of monocyte-derived cells during subsequent infections." (PMID 34611166, 2021). "Shown are the frequencies of spike-specific CD4+ (left) and CD8+ (right) T cells stimulated by the three spike proteins (squares: ancestral; triangles: B.1.1.7; circles: B.1.351) among the infection-naïve (aqua) and convalescent (coral) donors, after removal of outlier PID4112." (PMID 34636722, 2021). "There was, however, a trend where most high replicators progressed faster to CD4+ counts of less than 350 cells/μL in the first 5 years of infection, although this was not statistically significant." (PMID 33498793, 2021). "CD4+ T‐cell epitopes were screened by measuring peptides’ (9‐ to 10‐mer) ability to stimulate IFN‐γ production and bind to HLA2.1‐MHC‐I of DCs and protect mice against lethal infection challenge." (PMID 34176237, 2021). "However, if CD4 expression was the limiting factor for HIV infection in this setting, differential infection rates between T-PBMCs and T-Pure cells when exposed to CXCR4-tropic HIV would be expected." (PMID 34899645, 2021). "In 2017, we described a new role for transmembrane TNF-α (tm-TNF-α), facilitating the infection of CD4-negative podocytes and tubular epithelial cells cultured from children with HIV-associated kidney diseases." (PMID 33044676, 2021). "CD4+ T cells perform many essential functions, including stimulating B cells to mature and secrete antibodies and supporting cytotoxic CD8+ T cells and phagocytes to mount rapid and effective protection against infections." (PMID 34950144, 2021). "Latent and productively infected tonsillar CD4+ T cells displayed similar activation profiles as measured by expression of CD69, CD25, and HLADR, however latent cells showed higher CXCR5 expression 3 days post-infection." (PMID 34531866, 2021). "In addition, the functional state CS3 is the most different with the expression of Cd86, Cd4, and especially Ccl22, suggesting this state to be actively recruiting other cells, such as invariant NKT or regulatory T cells, in response to the infection." (PMID 34404761, 2021). "There was a significant increase in PD-1-expressing T-cell subsets during SS including PD-1+/CD4+ TCM (P = 0.0018) and PD-1+/CD4+ TEM (P = 0.0165) as well as PD-1+/CD8+ TCM (P = 0.0270) and PD-1+/CD8+ TEM (P = 0.0106) compared to before infection." (PMID 34349746, 2021). "In addition, CD4+ SARS-CoV-2-Spike-tetramer cells in PBMC on 7 and 14 dpi were obviously higher than the levels before infection." (PMID 34060982, 2021). "Trans-infection represents one mechanism of cell contact-dependent enhancement of CD4+ T cell infection, but is not the only one." (PMID 33976386, 2021). "We have now shown that both HIV and HSV can infect epidermal LCs and Epi-cDC2s, so they may be sites for synergistic infection in the same or, more likely, adjacent cells and/or act as a facilitated conduit for HIV to transfer to dermal CD4+ T cell targets." (PMID 33905459, 2021).
infection (continued). "Given that CD4+ T cells and B cells are viewed as the predominant cellular sources of RANKL in some inflammatory conditions, we evaluated the distribution of RANKL+ cells in mesenteric lymph nodes and spleens during infection." (PMID 33735306, 2021). "Naïve CD4+ T cells purified from Ddb1-TaKO-SMARTA (CD45.1+) and WT-SMARTA (CD45.1+ CD45.2+) mice were mixed at ratio of 1:1, and then were adoptively transferred into congenic WT recipient mice (CD45.2+) followed by LCMV Armstrong infection." (PMID 34526995, 2021). "Infection correlates to an extensive infiltration of the neutrophils and macrophages into the lungs that leads to pro-inflammatory cytokine production, and, in addition, involves CD8+ and CD4+ T cells that orchestrate the immune response against viruses." (PMID 34439967, 2021). "Within the lung tissue of Clarithromycin-treated mice, we found diminished frequencies and numbers of CD4+ IL-17A+ T cells when compared with mock treatment, while the frequency and numbers of CD4+ IFN-gamma+ T cells were unimpaired 7 days post-infection (p.i.)." (PMID 33595670, 2021). "Here, however, we have demonstrated using more precise immunophenotyping (CD4+CD25+CD127−Foxp3+) methods and absolute number counts that increased values of Tregs are not limited to infection with HIV but are present in HCV-infected and HCV/HIV-coinfected patients as well." (PMID 34452314, 2021). "In the early phase after FCV Challenge I, all lymphocyte subsets (CD4+, CD8+, CD45R/B220+, CD5+, and CD5+/MHCII+) in all cats decreased in absolute numbers and returned to the preinfectional level by day 22 after challenge infection, except for CD4+/CD25+." (PMID 34578316, 2021). "The latent reservoir in peripheral CD4+T cells, during the asymptomatic phase of FIV-C infection, was found to be approximately one in 103 cells, of which only one in 102 was also replication competent, resulting in an overall infection rate of around one in 105 cells." (PMID 34452500, 2021). "This may not however be the entire immune profile required to contain infection, as TB reactivation in HIV individuals has been observed prior to a depletion of CD4+ T cells." (PMID 35222350, 2021). "At least some of these host transmembrane proteins on the surface of virions are reported as pro-viral factors that enhance virus attachment to target cells or facilitate trans-infection of CD4+ T cells via interactions with non-T cells." (PMID 34696365, 2021). "As this is not the case, we believe that CD4 expression is not the primary reason for the observed differential infection rates, although further investigations are needed to confirm this." (PMID 34899645, 2021). "Thus, our results reveal that all LECs respond to infection by increasing MHC-II on their surface, and LEC MHC-II mediates antigen presentation to CD4+ T cells." (PMID 34611166, 2021). "We further showed that CD4+ T cells isolated from acute L. sigmodontis-infected C57BL/6 donor mice or mice that already cleared the infection were able to eliminate the parasite and prevent inflammation at the site of infection." (PMID 34868049, 2021). "The ability of miR-135a to disrupt CD4+ T cell proliferation in concert with expression of CCR5 is suggestive of its potentially important role in immune cell trafficking following infection." (PMID 33928045, 2021). "Infection with two subtype B T/F molecular clones lacking Vpu resulted in higher surface levels of Tim-3 in CD4+ T cells." (PMID 34358561, 2021). "While multiple lines of evidence support a central role of CD8+ and CD4+ T cells in the control of HCV infection, the role of antibodies in resolving infection and, by extension, their potential protective value in vaccine-elicited responses, has been less clear." (PMID 34372558, 2021). "The low dose infected group demonstrated a consistent measure of the CD4+ IL-17+T cells from week 1 to week 3 post-infection with no significant changes compared to the pre-infection levels." (PMID 34484203, 2021).
infection (continued). "Consistent with a role for CD4+ T cell help for CD8+ T cells, CD4+ T cell depletion prior to i.n. infection significantly reduced the frequency and number of MCMV-specific CD8+ T cells in the blood, sharply impairing the normally dominant responses against the M45 and M38 antigens." (PMID 33508041, 2021). "The significance of the infection of macrophages by HIV is well established in the fact that as the infection progresses, CD4+ T-cells are depleted and individuals become increasingly macrophage-tropic; with macrophages becoming the main long-lived HIV reservoir." (PMID 33861800, 2021). "Also similar to the CD4+ T cells, spike-specific CD8+ T cells elicited by vaccination differed phenotypically in the infection-naïve vs. convalescent individuals." (PMID 34636722, 2021). "Overall, these results indicate that ART during the hyperacute phase of HIV infection prevented immune activation of the CD4+ and CD8+ T cell populations, and that initiation of ART during the chronic infection phase reduced immune activation to baseline pre-infection levels." (PMID 34630420, 2021). "Additional studies showed that upon the stimulation of human PBMC from seropositive individuals, or those who had recovered melioidosis, that NK cells were transient and predominated during the first 24 hours while CD4+ and CD8+ T cells were more important in the later phases of infection." (PMID 34394091, 2021). "The early initiation of antiretroviral therapy (ART) during the acute phase of infection limits HIV-1 reservoir seeding and immune activation (27, –29) and preserves important subsets of CD4+ T cells in the gut mucosa, whereas the fate of iNKT cells has not been studied." (PMID 34753817, 2021). "The third, M-tropic HIV, can use CCR5, CXCR4 or both coreceptors, and arises in some individuals late in infection and in T cell-depleted environments such as in advanced HIV-1 disease, in the central nervous system, or in settings of experimental depletion of CD4+ T cells." (PMID 33594125, 2021). "This is particularly clear for CD4 T cells from M. bovis-infected animals, where cells displaying dual function (proliferation and IFN-γ) now constitute ~44, 40, and 22% of the response at 4-, 8-, and 48-weeks post-infection, respectively." (PMID 34336973, 2021). "This is despite the presence of a similar frequency of virus-specific CD4+ T cells in neonates to that seen after adult infection, suggesting it is not simply due to reduced antigen presentation." (PMID 34665220, 2021). "Bars show the fraction of contracting CD4+ and CD8+ TCRbeta clonotypes present in 2 year; 1 year pre-infection PBMC; in at least one of memory subpopulation sampled on day 30, day 37, and day 85 post-infection." (PMID 33399535, 2021). "Notably, a higher percentage of CD4+CD8+ double-positive cells was found in the thymus of N. caninum-infected fetuses at 10 dpi, indicating an active response against an ongoing infection." (PMID 34239816, 2021). "Notably, T cell responses were shown to be polyfunctional (involving both CD4+ and CD8+ lymphocytes), stable, and lasting for at least six months after infection, even though anti-SARS-CoV-2 antibodies decline with time." (PMID 34067349, 2021). "No outgrowth was detected in healthy donor’s CD4+ T cells (serving also as infection reporter cells) after interaction with HIV-containing platelets from InRs, even in the presence of polybrene, a facilitator of membrane fusion (left)." (PMID 35222352, 2021). "Anti-CD4 monoclonal antibody (MAb) treatment of immune mice restricted the protective immune response against challenge infection; however, anti-CD8 MAb treatment did not affect protection." (PMID 34414129, 2021). "Like CD4+ T cells, a portion of CD8+ T cells survive as memory T cells following infection." (PMID 34299120, 2021).
infection (continued). "In tissues treated prior to infection, baseline production of IL-1β, IL-22, CCL3, CCL4 and CCL5 varied between BaL- and LAI-infected explants, possibly reflecting virus difference in cell tropism and subsequent CD4 T cell depletion." (PMID 34835109, 2021). "During the acute phase of the infection, iNKT deficiency was associated with a lower frequency of CD69-expressing CD8+, but not CD4+, T cells indicating their suboptimal activation." (PMID 33954206, 2021). "However, the percent of activated/proliferating CD4+ and CD8+ T cells in response to antigenic stimulation was significantly higher in Mtb-AG than Mtb-SC-infected animals at both 2 and 4 weeks post infection." (PMID 34732811, 2021). "VISTA was not upregulated by Foxp3− CD4+ T cells during infection in any of the three mouse strains indicating a minor role for VISTA in the regulation of anti-helminth immune responses." (PMID 33452272, 2021). "Moreover, SCFAs regulate systemic lymphocyte responses mediated by CD4 T cells, CD8 T cells, B cells, and ILCs during infection." (PMID 33850311, 2021). "Decidua from 10 ZIKV-infected dams obtained 16-56 days post infection at third (n=9) or second (n=1) trimester showed a significant reduction in frequency of activated, CXCR3+, and/or Granzyme B+ memory CD4+ and CD8+ T lymphocytes and γδ T compared to normal decidua." (PMID 34394129, 2021). "We then tested whether CD4 and CD8 T cells were required for the invasion of leukocytes and parasites into the ME early after infection." (PMID 34587172, 2021). "During the early stages of infection, IL-10 overexpression altered neither populations of antigen-presenting cells (APCs) in the mediastinal lymph nodes (MLNs) nor the kinetics of CD4+ T cell activation." (PMID 34554927, 2021). "Five days following re‐infection, we found significant increases in the numbers of antigen‐specific CD4 T cells in the lungs and MedLN of mice regardless of their immunisation history." (PMID 32931017, 2021). "Recent evidence also showed that a low percentage of circulating CD4+ and CD8+ T cell count might reflect the severity of the infection and is often accompanied by a poor prognosis." (PMID 34626490, 2021). "P. falciparum-induced upregulation of IL-10 production by CD4+Foxp3- Th1 cells rather than T regs, is usually sustained in persistent asymptomatic infection." (PMID 33746974, 2021). "Similar observations show CD4+ T cells levels relative to those with AKI and infection." (PMID 34869652, 2021). "First, as PLWHA without infection TB, INIs had more motivation in terms of CD4+ recovery compared with EFV." (PMID 33933131, 2021). "Even though the levels of CD4+ T cells are much lower as compared to CD8+ T cells in the brain of infected mice, they are similarly important for the control of virus replication in the brain and resolution of productive infection." (PMID 34200083, 2021). "Although prophylactic treatment with rapamycin decreased HIV-1 susceptibility of epithelial LCs, it did not reduce infection of subepithelial CD11c+ DCs or CD4+ T cells." (PMID 33637808, 2021). "The present study evaluated the influence of ART on the expression of STING and cGAS, the production of type I IFN, and the levels of laboratory markers often used to monitor infection (CD4+, CD8+, and ratio of CD4+/CD8+ T cells and viral load) in a cohort infected with HIV-1." (PMID 33858455, 2021). "We found that unlike pre-incubation, pEV treatment post-infection did not impact the frequency of p24+ CD4+ T cells." (PMID 34249000, 2021). "HIV-1 can establish a stably integrated, non-productive latent state of infection of individual cells, mainly in long lived CD4+ T cells that are maintained by homeostatic proliferation." (PMID 34717655, 2021). "Of note, when these supernatants were collected and added to fresh tonsil cultures, little or no productive infection was observed and no CD4 T-cell killing was detected after 48 h (data not shown)." (PMID 34418431, 2021).